CRYGA (crystallin gamma A)
Description:
Crystallins are the dominant structural components of the vertebrate eye lens.
Synonyms: CRYG1; CRYG5; CRY-g-A
Tractability: No criterion of Open Targets' tractability assessment is met for any kind of drug.
Gene: Protein-coding gene on chromosome 2 (208,160,740 to 208,163,589, reverse strand). Ensembl gene ENSG00000168582.
Subcellular location (Human Protein Atlas): Cytosol; Vesicles
Gene Ontology:
Molecular function: structural constituent of eye lens
Biological process: lens development in camera-type eye; visual perception
Genetic constraint (gnomAD): Loss-of-function variants: 16 observed, 19.51 expected, observed/expected ratio (o/e) 0.82, 90% interval 0.55 to 1.25. The upper end of that interval is the gene's LOEUF score, 1.25, which puts it in group 5 of 6, group 1 being the genes least tolerant of losing a copy. Missense variants: 224 observed, 208.35 expected, observed/expected ratio (o/e) 1.08, 90% interval 0.96 to 1.2. Synonymous variants: 83 observed, 78.07 expected, observed/expected ratio (o/e) 1.06, 90% interval 0.89 to 1.28.
Homologues: Orthologues: chimpanzee CRYGA (100% identical), macaque CRYGA (98% identical), mouse Cryga (84% identical), rabbit CRYGA (84% identical), guinea pig CRYGA (83% identical), rat Cryga (83% identical), dog CRYGA (81% identical). Paralogues in human: CRYGC (75% identical), CRYGB (74% identical), CRYGD (72% identical), CRYGS (51% identical), CRYBB1 (34% identical), CRYBA2 (34% identical), CRYBA4 (34% identical), CRYBB3 (34% identical), CRYBB2 (33% identical), CRYBG2 (33% identical), CRYBA1 (32% identical), CRYBG1 (32% identical), and 2 more.
Diseases named in the same sentence as CRYGA in open-access papers:
CRYGA is named in the same sentence as 3 diseases in open-access papers, as found by Europe PMC text mining. Sharing a sentence is not in itself a finding about the gene and the disease. The quoted sentences say what the papers report.
autosomal dominant congenital cataracts (1 paper, 2022). "Overall, we report four novel mutations in HSF4, CRYGA, CRYGC and PAX6, and one previously reported mutation in GJA3 that cause autosomal dominant congenital cataracts." (PMID 36670602, 2022).
CRYGA also shares sentences with these, for which no sentence is quoted: cataract (2 papers); liver cancer (1).